CEACAM6 (CEA cell adhesion molecule 6)
Diseases named in the same sentence as CEACAM6 in open-access papers (continued):
Sharing a sentence is not in itself a finding about the gene and the disease.
bladder cancer (3 papers, 2017 to 2025). "Our study found a significantly elevated CEACAM6 expression in TRIM9 high expressed bladder cancer and it was associated with poor survival of patients." (PMID 37249822, 2023). "Researchers isolated 67LR+/CK17+/CEACAM6-cells from the human bladder cancer cell line SW780 and bladder cancer samples." (PMID 40635786, 2025). "Collectively, those results suggested that TRIM9 mediated bladder cancer progression through CEACAM6." (PMID 37249822, 2023). "Mechanically, we further demonstrated that the overexpressed TRIM9 increased tumor cells proliferation, migration and drug resistance via CEACAM6-Smad2/3 signaling activation in bladder cancer." (PMID 37249822, 2023). "Motivated by our previous evidence that TRIM9 promoted CEACAM6-Smad2/3 signaling to facilitate bladder cancer cell proliferation/migration, we next sought to evaluated the influence of TRIM9 on tumor growth in vivo." (PMID 37249822, 2023). "Together, those data indicated that TRIM9/CEACAM6 mediated Smad2/3 signaling activation to modulate bladder cancer progression." (PMID 37249822, 2023). "Remarkably, this study, for the first time, indicated that CEACAM6 played an important role in the TRIM9 induced bladder cancer progression." (PMID 37249822, 2023). "Secondly, our exploration about effects of TRIM9 on cell biological processes showed that TRIM9 promoted bladder cancer proliferation, migration and chemoresistance via CEACAM6/Smad2/3 signaling." (PMID 37249822, 2023). "In summary, our experiments suggest that TRIM9 plays an oncogenic role in bladder cancer progression by increasing cell proliferation, migration, and inducing chemoresistance via CEACAM6/Smad2/3 signaling pathway." (PMID 37249822, 2023). "Furthermore, we demonstrated that TRIM9 promoted bladder cancer progression and chemoresistance through the regulation of cell proliferation, apoptosis, migration via CEACAM6-Smad2/3 signaling." (PMID 37249822, 2023). "Importantly, immunostaining results further confirmed elevated expression of CEACAM6 in recurrent bladder cancer patients." (PMID 37249822, 2023). "Since previous studies have suggested that CEACAM6 could be a potential target for different cancer immunotherapies, our evidences further highlighting its role as both a prognostic and a therapeutic target in bladder cancer." (PMID 37249822, 2023). "In addition, TGF-β induced MMPs expression has been shown to enhance the invasion and migration capabilities of various cancer cells, and our study also identified an increased MMP2 expression in the CEACAM6/Smad2/3 signaling medicated bladder cancer progression." (PMID 37249822, 2023).
colon adenocarcinoma (3 papers, 2007 to 2024). "Without additional stratification, there was no emergent association between CEACAM5 or CEACAM6 levels and overall survival or disease-free survival among colon adenocarcinoma patients." (PMID 38502695, 2024). "Much larger amounts of CEACAM6 were found in colon adenocarcinoma (6.2 ± 1.4) compared with non-neoplastic colon (3.0 ± 0.0; P < 0.002) and CEACAM6 expression exceeded CEACAM5 expression (3.4 ± 0.5; P < 0.001)." (PMID 17201906, 2007).
colorectal adenocarcinoma (3 papers, 2014 to 2024). The most common type of colorectal carcinoma. "Furthermore, over-expression of CEACAM6 is associated with a poorer prognosis of patients with colorectal adenocarcinoma following surgical resection, and is a very useful marker for the follow-up of these patients in the clinic." (PMID 24625834, 2014). "Most colorectal adenocarcinomas (18 out of 19 cases) were positive for CEACAM6." (PMID 25427744, 2015).
COVID-19 (3 papers, 2021 to 2025). A disease caused by infection with severe acute respiratory syndrome coronavirus 2. "A significant increase in the number of developing neutrophils was found in COVID-19 while CEACAM1, CEACAM6 and CEACAM8 were also significantly co-localized developing neutrophils." (PMID 34217339, 2021). "In COVID-19, we also found that CEACAM8 is highly expressed in the developing neutrophils/neutrophil progenitors, while CEACAM5 and CEACAM6 are highly expressed in type II pneumocyte." (PMID 34217339, 2021). "When the blood transcriptomic profiles of patients with mild COVID-19 were compared with the profiles from patients with moderate or severe COVID-19, CEACAM8, MMP8, ELANE, LTF, CEACAM6 and MPO were consistently amongst the top SDE genes, with levels increasing with severity and high LFCs." (PMID 35844004, 2022). "CEACAM6 has been identified as having high expression in Type II pneumocytes in COVID-19 patients, the cells targeted by SARS-CoV-250, and it has been suggested that cross-talk between Type II pneumocytes and developing neutrophils in COVID-19 occurs via CEACAM8-CEACAM649." (PMID 35844004, 2022).
gastritis (3 papers, 2016 to 2025). Inflammation of the stomach. "In relation to HopQ specifically, CEACAM1, CEACAM5 and CEACAM6 are all upregulated in gastritis caused by chronic H. pylori infection, again suggesting a mechanism for H. pylori promoting its own persistence in an inflammatory environment." (PMID 38615147, 2024). "The lower expression of CEACAM6 in regions of chronic gastritis is also significant, as a putative marker would ideally need to distinguish pre-neoplastic lesions from gastritis, which is far more prevalent in patients with H. pylori." (PMID 27421133, 2016). "HIF1α, CEACAM6, and NOX4 upregulation was detected in gastritis and GC tissues." (PMID 40325849, 2025).
inflammatory bowel disease (3 papers, 2011 to 2022). A spectrum of small and large bowel inflammatory diseases of unknown etiology. "Given its contribution to the pathogenesis of CD, we aimed to investigate the role of genetic variants in the CEACAM6 region in patients with inflammatory bowel diseases (IBD)." (PMID 21559399, 2011).
influenza (3 papers, 2021 to 2024). An acute viral infection of the respiratory tract, occurring in isolated cases, in epidemics, or in pandemics; it is caused by serologically different strains of viruses (influenzaviruses) designated A, B, and C, has a 3-day incubation period, and usually lasts for 3 to 10 days. "In our analysis, the module was associated with neutrophil activation (P = 5E−22), indicating CEACAM6 as a potential biomarker for severe influenza that requires mechanical ventilator support." (PMID 38071387, 2023). "We found that the M59 hub gene CEACAM6 and its co-expressing CEACAM8 were both up-regulated in the influenza dataset." (PMID 38071387, 2023).
lymph node metastasis (3 papers, 2017 to 2022). "Another research group also demonstrated that CEACAM6 was associated with the tumorigenesis and lymph node metastasis." (PMID 29137373, 2017). "However, high CEACAM6 expression was associated with poor OS in patients with lymph node metastasis (P < 0.01)." (PMID 28883649, 2017). "The proportion of positive CEACAM6 statistically correlated with tumor size, Lauren's classification, vascular invasion, lymph node metastasis, distant metastasis, and TNM stage." (PMID 29137373, 2017). "CEACAM6 was detected in 65.9% (178/270) of GC specimens with lymph node metastasis, which was higher compared with those without lymph node metastasis (15.7%, 26/166, p=0.000)." (PMID 29137373, 2017).
metastatic tumors (3 papers, 2012 to 2024). "Our data suggest that targeting CEACAM6 may be ineffective in metastatic tumors of the lymph nodes and early-stage tumors; therefore, other therapies may be more appropriate in these instances." (PMID 38502695, 2024).
mucinous adenocarcinoma (3 papers, 2007 to 2020). An invasive adenocarcinoma composed of malignant glandular cells which contain intracytoplasmic mucin. "Among these genes, CEACAM6 (−log10P‐adj = 67.71, log2FC = 4.27) is a carcinoembryonic antigen cell‐adhesion molecule and a biomarker for mucinous adenocarcinoma." (PMID 33377642, 2020). "Consistent with this, we found that seven out of eight mucinous carcinomas (88 %) but only one case of serous carcinoma (17 %) stained positive for CEACAM6 using the AP11 antibody." (PMID 25427744, 2015).
squamous cell carcinoma (3 papers, 2007 to 2025). A carcinoma arising from squamous epithelial cells. "We did not detect CEACAM6 expression in SCLC, while adenocarcinomas and squamous cell carcinomas frequently expressed CEACAM6 (83 and 60 %, respectively)." (PMID 25427744, 2015). "CEACAM6 expression in large cell and poorly differentiated squamous carcinomas was similar to non-neoplastic lung tissue, and SCLC also expressed CEACAM6." (PMID 25427744, 2015).
cervical cancer (2 papers, 2020 to 2025). A primary or metastatic malignant neoplasm involving the cervix. "In the study of cervical cancer, the expression of CEACAM5 and CEACAM6 was similar in five different histological subtypes, with no significant statistical difference." (PMID 40046734, 2025). "We further validated that the overexpression of miR-128 markedly decreased ITGA5, ITGB5, sLex, CEACAM-6, MMP-9, and MMP-23 in SSR-HeLa and SSR-CaSki cervical cancer cell clones." (PMID 33379338, 2020). "After validation by quantitative RT-PCR, we discovered that diminished miR-128 in WT-HeLa or WT-CaSki cells markedly increased the expression levels of ITGA5, ITGB5, sLex, CEACAM-6, MMP9, and MMP23 in WT-HeLa and WT-CaSki cervical cancer cell clones." (PMID 33379338, 2020).
cholesteatoma (2 papers, 2012 to 2014). A pathologic process characterized by the proliferation of keratinizing squamous epithelium resulting in the accumulation of keratin and cells in the middle ear and/or mastoid. "The cell adhesion protein CEACAM6 was found to be highly up-regulated in cholesteatoma compared with the tympanic membrane and EACS, in particular." (PMID 25093596, 2014). "CEACAM6 is emerging as an important determinant of the malignant phenotype in a range of cancers; in cholesteatoma this gene is also up-regulated (logFC 2)." (PMID 23285167, 2012). "Real-time PCR of PI3, SPRR1B, LCN2 (lipocalin 2), MMP1, MMP9, MMP10, MMP12, SPP1, GJB2, Bcl-xl (BCL2L1), cIAP2 (BIRC3), S100A7A (koebnerisin), S100A9, SERPINB3, CEACAM6, KRT6B and SERPINB4 revealed that the expression levels of these proteins were higher in cholesteatoma than in external canal skin." (PMID 23285167, 2012).
Colorectal Tumor (2 papers, 2007 to 2024). "In colorectal tumors matched with normal adjacent tissues, we observed a strong increase in both CEACAM5 and CEACAM6 levels in tumor tissues, compared to normal tissues." (PMID 38502695, 2024).
cystic fibrosis (2 papers, 2011 to 2018). Autosomal recessive disorder caused by pathogenic variants in the CFTR gene (cystic fibrosis transmembrane conductance regulator), which encodes a chloride and bicarbonate channel expressed in epithelial cells, and follow the diagnosis criteria. "Interestingly, a recent study indicated that CEACAM6 and a regulatory element near the 3′ end of CEACAM3 are associated with disease severity in patients with cystic fibrosis." (PMID 21559399, 2011). "In azurophilic granules in pathogen-infected sputa from individuals with cystic fibrosis, Thaysen-Andersen and co-authors identified a paucimannosidic glycan on CEACAM6 with 2 GlcNAc and 2 Man, with or without Fuc." (PMID 29720971, 2018).
dysplasia (2 papers, 2007 to 2021). A usually neoplastic transformation of the cell, associated with altered architectural tissue patterns. "The rather frequent non-focal transition to colonic tissue with features of dysplasia observed in CEABAC20 mice suggests that over-expression of CEA and/or CEACAM6 to a critical threshold level alone is sufficient to initiate the transformation of a normal epithelium to a state of dysplasia." (PMID 18159236, 2007).
gastric tumor (2 papers, 2017 to 2021). "Subsequently, immunohistochemical staining was performed to determine CEACAM6 protein levels in paraffin gastric tumor specimens." (PMID 29137373, 2017). "In our previous study, we found CEACAM6 was up regulated (ratio ≥ 2) in gastric tumor tissues by performing the Affymetrix GeneChip HG-U133A2.0 array." (PMID 29137373, 2017).
hyperplastic polyp (2 papers, 2007 to 2015). A polyp found mainly in the stomach and colon. "Four of five tubular adenomas (80 %) and four of five hyperplastic polyps (80 %) stained positive for CEACAM6." (PMID 25427744, 2015).
lung squamous cell carcinoma (2 papers, 2015 to 2022). "Exosomal TP63, KRT5, CEACAM6, and SFTPB mRNAs can be used as biomarkers to differentiate between lung squamous cell carcinoma (LUSC) and lung squamous cell carcinoma (LUAD), thereby, providing a novel strategy for their differential diagnosis and treatment." (PMID 35584089, 2022).
Merkel Cell Carcinoma (2 papers, 2024). "The study of CEACAM6 in the differentiation of Merkel cell carcinoma and SCLC provides ideas for the differentiation of primary skin malignancies and secondary malignancies, and we hope to have related studies in the future." (PMID 38796667, 2024).
metastasis (2 papers, 2017 to 2023). The spread or migration of cancer cells from one part of the body (where they first appeared) to another. "The IHC staining intensity of CEACAM6 was positively correlated with tumor size, Lauren's classification, vascular invasion, lymph node metastasis, distant metastasis, and TNM stage." (PMID 29137373, 2017).
Mucinous tumor (2 papers, 2007 to 2015). "Mucinous tumor CEACAM6 expression was significantly higher than transitional and endometroid (P < 0.02), clear cell (P < 0.01), and yolk sac tumors (P < 0.005)." (PMID 17201906, 2007). "Thus, mAb AP11-stained CEACAM6 may serve as a marker for mucinous tumors." (PMID 25427744, 2015).
myeloid leukemia (2 papers, 2019 to 2023). A clonal proliferation of myeloid cells and their precursors in the bone marrow, peripheral blood, and spleen. "CEACAM6 is particularly applicable in myeloid leukemia and colon adenoma, and therapeutic antibodies against CEACAM6 have also been tested in clinical trials." (PMID 38072118, 2023).
oral squamous cell carcinoma (2 papers, 2022 to 2024). "In oral squamous cell carcinoma, overexpression of carcinoembryonic antigen-related cell adhesion molecule 6 (CEACAM6) also potentiates the EGF-induced EGFR phosphorylation, activation of the MAPK and Akt signaling pathways, and cell migration." (PMID 39594667, 2024). "Morever, overexpression of GnT-V glycosyltransferase enhances CEACAM6 N-glycosylation to predict recurrence of oral squamous cell carcinoma." (PMID 35879690, 2022).
Sepsis (2 papers, 2022 to 2025). Sepsis is defined as life-threatening organ dysfunction caused by a dysregulated host response to infection. "Indeed, we found elevated abundance levels of CEACAM6 in patients with infections caused byStaphylococcus aureus, influenza, respiratory syncytial virus, human immunodeficiency virus, and bacterial pathogens causing sepsis, in comparison with controls." (PMID 39239252, 2022). "Only a small number of host genes were differentially expressed between the Gram-positive (HLA-B, SERPINB10, LOC105377885, CEACAM6, NIPA2) and Gram-negative (CBFA2T3, LOC107987303, MARCO) sepsis samples in our cohort." (PMID 40965975, 2025).
ulcerative colitis (2 papers, 2011 to 2021). An inflammatory bowel disease involving the mucosal surface of the large intestine and rectum. "Haplotypes of CEACAM6 SNPs in ulcerative colitis (UC) case-control sample and omnibus p-values for association with UC susceptibility." (PMID 21559399, 2011). "Analysis for linkage disequilibrium between CEACAM6 SNPs in patients with ulcerative colitis." (PMID 21559399, 2011).
adenovirus infection (1 paper, 2016). "In addition, CEACAM6 was reported to attenuate the adenovirus infection in cancer cells by antagonizing intracellular trafficking." (PMID 27690085, 2016).
bacterial sepsis (1 paper, 2022). "An increase in levels of CEACAM6 transcripts has been reported in the literature and observed in blood transcriptome datasets for patients with infectious (e.g., bacterial sepsis), autoimmune, or inflammatory diseases (e.g., systemic lupus erythematosus, Kawasaki disease)." (PMID 39239252, 2022).
bone metastasis (1 paper, 2023). Transfer of a neoplasm from its primary site to bones. "Additionally, serum CEACAM6 was much higher in LM than other metastases such as brain metastasis and bone metastasis." (PMID 36082960, 2023).
chronic gastritis (1 paper, 2016). Inflammation of the stomach that is chronic in nature. "In contrast, minimal staining of CEACAM6 occurred in regions of chronic gastritis, the most prevalent lesion associated with H. pylori infection." (PMID 27421133, 2016).
chronic pancreatitis (1 paper, 2021). A chronic inflammatory process causing damage and fibrosis of the pancreatic parenchyma. "Furthermore, we evaluated CEACAM6 and the conventional biomarkers carcinoembryonic antigen (CEA) and carbohydrate antigen 19-9 (CA19-9) concentrations in blood serum samples from patients with PDAC, chronic pancreatitis (CP), and healthy controls (HC)." (PMID 34207784, 2021).
clear renal cell carcinomas (1 paper, 2015). "CEACAM6 was expressed in a subset of clear renal cell carcinomas and urothelial carcinomas (14 and 13 %, respectively)." (PMID 25427744, 2015).
Down syndrome (1 paper, 2005). "In one specimen (ALL patient with Down syndrome), CEACAM6 wasn't increased in CD66cpos fraction." (PMID 15826304, 2005).
ductal carcinomas of the breast (1 paper, 2015). "Only one out of nine ductal carcinomas of the breast showed CEACAM6 expression, whereas no papillary thyroid carcinoma displayed CEACAM6 expression." (PMID 25427744, 2015).
Duodenal polyposis (1 paper, 2019). Presence of multiple polyps in the duodenum. "We also identified CEACAM6 as a potential novel therapeutic target for duodenal polyposis control in FAP." (PMID 31211760, 2019). "Effect of the CEACAM6 antibody-drug conjugate on APCMin/+ mice can also be investigated, and if this shows therapeutic benefit and low toxicity, targeting CEACAM6 may emerge as a viable option for duodenal polyposis control in FAP." (PMID 31211760, 2019).
head and neck cancer (1 paper, 2012). A primary or metastatic malignant neoplasm affecting the head and neck. "A recent transcriptomic profiling study comparing highly tumourigenic clonal variants of an established head and neck cancer squamous cell carcinoma (HNSCC) cell line with poorly tumourigenic clonal variants, identified a strong association between CEACAM6 expression and tumourigenic potential." (PMID 23021083, 2012).
head and neck squamous cell carcinoma (1 paper, 2012). A squamous cell carcinoma that arises from any of the following anatomic sites: lip and oral cavity, nasal cavity, paranasal sinuses, pharynx, larynx, and salivary glands. "Therefore, we examined the role of CEACAM6 in head and neck squamous cell carcinoma (HNSCC)." (PMID 23021083, 2012). "However, the mechanism of how CEACAM6 contributes to cancer formation and its role in head and neck squamous cell carcinoma (HNSCC) remains unclear." (PMID 23021083, 2012).
Hyperammonemia (1 paper, 2025). An increased concentration of ammonia in the blood. "Given the intended delivery of L-DOS47 to CEACAM6-expressing tumors and that urease activity would be localized to the TME, systemic ammonia should not increase appreciably at the L-DOS47 doses investigated here; indeed, no neurotoxic signs related to hyperammonemia were reported." (PMID 40860822, 2025).